TAP1 (transporter 1, ATP binding cassette subfamily B member)
Diseases named in the same sentence as TAP1 in open-access papers (continued):
Sharing a sentence is not in itself a finding about the gene and the disease.
TAP1 also shares sentences with these, for which no sentence is quoted: bladder cancer (4 papers); bladder urothelial carcinoma (3); lung squamous cell carcinoma (3); AIDS (2); allergic rhinitis (2); ankylosing spondylitis (2); breast invasive carcinoma (2); cervical neoplasm (2); Epstein-Barr virus infection (2); esophageal adenocarcinoma (2); esophageal squamous cell carcinoma (2); germ cell tumor (2); Graves disease (2); oral squamous cell carcinoma (2); paraganglioma (2); rheumatoid arthritis (2); sarcoma (2); thymoma (2); acute myeloid leukemia (1); adrenocortical carcinoma (1); allergic asthma (1); Alzheimer disease (1); Anxiety (1); blood cancers (1); brain tumors (1); cervical squamous cell carcinoma (1); Chagas disease (1); Childhood onset (1); Chlamydia infection (1); cholangiocarcinoma (1).
A further 47 diseases each share a sentence with TAP1 in 1 paper.